IL10 (interleukin 10)
Diseases named in the same sentence as IL10 in open-access papers (continued):
Sharing a sentence is not in itself a finding about the gene and the disease.
leprosy (71 papers, 2009 to 2025). Leprosy is a chronic infectious disease affecting primarily the skin and peripheral nervous system. "We observed higher expression of PD-1 on Tregs is associated with lower production of IL-10 in leprosy patients." (PMID 37153623, 2023). "The possibility of hyporesponsiveness of T cells in leprosy patients has been investigated in several studies as being caused by several factors, including foamy macrophages in the presence of IL-10 and Tregs." (PMID 37153623, 2023). "Increased IL-10 production is linked to reduced IL-17 production, which contributes to the progression of MB-type leprosy." (PMID 37909507, 2023). "Certain studies have suggested that mutations in the TLR1 gene, which change the amount of IL-10 and tumor necrosis factor in macrophages, raise the risk of leprosy in Brazil and India." (PMID 38481606, 2023). "Some genes, such as NOD2, CCDC122-LACC1, TNF, TLR1, IFNG, and IL10, have already been associated with leprosy susceptibility after being consistently replicated in different populations." (PMID 35703715, 2022). "IL-10 together with IL-4 is known to be associated with LL pole and MB leprosy while IFN-γ associated with other proinflammatory cytokines and characterized the TT pole and PB leprosy." (PMID 36053342, 2022). "To evaluate the association of cytokine gene polymorphism on its function, we tested leprosy patients and quantified IL-10 levels in various genotype −819 C/T and −1082 G/A." (PMID 32849660, 2020). "And two meta analyses focusing on IL10 variants both confirmed the significant susceptibility association between−819 C/T (rs1800871) and leprosy." (PMID 32373110, 2020). "Our data point-outs the conclusive association of the −819TT and −1082 GG genotypes with the susceptibility of leprosy and suggests that these polymorphisms have remarkable role in higher production of IL-10 by T helper and T regulatory cells." (PMID 32849660, 2020). "Since leprosy is a chronic inflammatory disease and its severity is associated to the host immune response, and the level of IL-10 production can be vital to define disease outcome." (PMID 32849660, 2020). "Mutations occurred more often in the IL-10 (anti-inflammatory cytokine) promoter gene than in the TNF-α (pro-inflammatory) promoter gene in all leprosy groups." (PMID 32849660, 2020). "Our laboratory have previously reported the association of increased levels of IL-10 in lepromatous leprosy patients with high bacterial load of M. leprae and suppressed immune system of the host." (PMID 32849660, 2020). "Variant−819 C/T (rs1800871) in the promoter region of gene IL10 was repeatedly found to be associated with leprosy." (PMID 32373110, 2020). "Reports suggests that polymorphisms of the IL-10 promoters at positions −1082 (G/A), −819 (C/T), and −592 (C/A) are associated with the resistance against leprosy in Brazilian, Indian groups and Columbian population." (PMID 32849660, 2020). "A recent family-based meta-analysis study actually confirmed an association between IL-10 promoter polymorphisms and leprosy." (PMID 27764137, 2016). "We found a total of 11 studies that evaluated the influence of IL10 polymorphisms and leprosy published between 2001–2015; all of them were case-control studies that were conducted in Brazilian, Indian, Malawian, Mexican, Colombian and Chinese populations." (PMID 26340474, 2015). "Subsequent studies have shown that the functional IL10 polymorphisms are also associated with pulmonary tuberculosis and leprosy in Indian population." (PMID 25941808, 2015). "Meta-analysis results from studies investigating leprosy association and IL10 promoter polymorphisms." (PMID 26340474, 2015). "Nevertheless, in a Brazilian population, the IL10-819T allele was associated with leprosy in both a case–control study and in a meta-analysis." (PMID 26793196, 2015). "This is in line with the associations of IL-10 genetic variants with development of leprosy and leprosy reactions." (PMID 26510990, 2015).
leprosy (continued). "In another study with Brazilian patients, the haplotype IL10-3575A/-2849G/-2763C was associated with resistance to leprosy and development of more severe forms of the disease, and the haplotype IL10-3575T/-2849A/2763C with susceptibility to LD." (PMID 26793196, 2015). "For some time, the immune suppression observed in lepromatous leprosy was linked with IL-10 production or by IL-10 gene polymorphisms, conferring susceptibility to leprosy." (PMID 25992795, 2015). "In the present study, we provided an updated pooled OR estimate strengthening previous findings for IL10 promoter polymorphisms and its association with leprosy." (PMID 26340474, 2015). "IL-10 has immunosuppressive properties and IL-10 genetic variants have been associated with leprosy development and reactions." (PMID 25210773, 2014). "This study represents the first time IL-10 deficiency has been investigated 1) in vivo, 2) at the site of infection and 3) over acute and chronic infection in an experimental leprosy model." (PMID 25210773, 2014). "IL-10 polymorphisms have been associated with leprosy resistance or susceptibility in several endemic populations, and variations in IL-10 expression have been noted in relation to the occurrence and treatment of reactions." (PMID 25210773, 2014). "A study on patients with leprosy showed that IL10 −819 T allele carriers produce lower levels of IL-10 when compared with non-T allele carriers." (PMID 23634300, 2013). "Significant associations with leprosy were observed for 8 polymorphisms (rs1800871, rs1800872, and rs1554286 of IL10, rs3171425 and rs7281762 of IL10RB, rs2228048 and rs744751 of TGFBR2, and rs1800797 of IL6)." (PMID 23936864, 2013). "The association of IL-10 (rs1800871) with leprosy has been firmly established." (PMID 38440733, 2024). "In addition, variant −819 C/T (rs1800871) in the promoter region of IL10 has repeatedly been associated with susceptibility to leprosy." (PMID 36972292, 2023). "IL-10 is a cytokine associated with the induction of a phagocytic and permissive macrophage phenotype in leprosy patients and we can suggest that the regulation of TREM2 after MDT in MB patients may impact the outcome of the treatment." (PMID 35937686, 2022). "In our study, homozygous IL-10 −1082 GG genotype was significantly higher in leprosy patients compared to the controls, due to the predominance of G allele suggesting an impact for allele G in leprosy susceptibility." (PMID 32849660, 2020). "Therefore, the goal of current study is to investigate the association of IL-10 cytokine gene polymorphisms with Th and Treg cells mediated production of IL-10 and its association with the susceptibility and progression of leprosy in Indian population." (PMID 32849660, 2020). "Therefore, we can conclude that IL-10 cytokine gene polymorphisms by affecting its production can determine the predilection and progression of leprosy in the study population." (PMID 32849660, 2020). "The markers included 11 SNPs selected to replicate the previously reported associations of the TLR1, NOD2, and IL6 genes and the remaining SNPs in 4 candidate genes TNF, LTA, IFNG, and IL10, in reference to markers previously associated with leprosy per se as an outcome." (PMID 28715406, 2017). "We have additionally investigated the classic candidate genes TNF/LTA, IFNG, and IL10, which were consistently associated with leprosy per se but, despite the central roles of these cytokines in leprosy reactions, were not genetically associated with reaction outcomes in our study." (PMID 28715406, 2017). "IFN-γ, TNF and IL-10 are mediators traditionally associated with leprosy pathogenesis per se." (PMID 27764137, 2016). "The first meta-analysis of IL10 polymorphisms and association with leprosy was published in 2009." (PMID 26340474, 2015). "TGF-β and IL-10 reported to be associated with FOXP3 cells were seen in both leprosy types." (PMID 24454972, 2014).
leprosy (continued). "Thus, the lower expression levels of DC-SIGN in A allele carriers could imply a low production of IL-10, concurring with the development of an efficient cell-mediated immune response observed in PB leprosy patients." (PMID 35703715, 2022). "The high TLR2 expression associated with IL-10 levels, in the leprosy reaction groups, may be hypothetically related to the formation of TLR2/2 homodimers and/or TLR2/6 heterodimers linked to evasion mechanisms in downgrading reactions and pathophysiology of ENL." (PMID 31781675, 2019). "High IL-10 producing allele of TLR2 microsatellite might predispose household contacts to leprosy." (PMID 26793196, 2015). "Interleukin-10 (IL-10) is a crucial immunomodulatory cytokine in mycobacterial pathogenesis and especially the -819C>T SNP (rs1800871) has been tested in several case-control studies indicating association with leprosy risk, although a recent consensus estimate is still missing." (PMID 26340474, 2015). "Based on the latest human genetic leprosy susceptibility research and mouse infection models, we generated a double knockout mouse strain (10NOS2−/−) which has deficiencies in two key immune factors, interleukin-10 (IL-10) and inducible nitric oxide synthase (NOS2)." (PMID 25210773, 2014). "GM-CSF enhances T cell response through macrophages by inhibiting IL-10, which is an encouraging development in the treatment of leprosy in new ways." (PMID 41306590, 2025). "Toll-like receptors (TLR) 1, TLR2, TLR4, dendritic cell-specific intercellular adhesion molecule-3-grabbing non-integrin (DC-SIGN), and CD163 mediate the interaction between macrophages and M. leprae in leprosy, which increases IL-6 and IL-10 secretion." (PMID 41239264, 2025). "In leprosy, Th2 stimulates the secretion of IL-10 and is responsible for inhibition of macrophage function, suppression of cell-mediated immunity, and antibody production." (PMID 41239264, 2025). "Patients with LL leprosy and, to a lesser extent, those with tuberculoid infection have been found to contain regulatory B-cells (Bregs) that produce IL-10." (PMID 39308868, 2024). "In leprosy patients, the cytokine IL-10 is expressed in greater concentration in MB patients and in those with leprosy reaction, although it is also present in the plasma of PB patients." (PMID 38381878, 2024). "Using UCP-LFA, CXCL10 was higher in response to M. leprae antigen and higher CXCL10/IL-10 ratio in leprosy patient compared to endemic control (EC)." (PMID 38590701, 2024). "Another point that can help in understanding the role of IL-10 and IL-13 PB and MB leprosy and corroborate with our data, concerns the analysis of IL-9 levels in leprosy patients in this study." (PMID 38381878, 2024). "Cytokines such as IL-1β and IL-23 induce Th17, while transforming growth factor beta and IL-10 inhibit Th17, indicating that the balance between Th17 and regulatory T cells is crucial for leprosy polarization." (PMID 37909507, 2023). "In several studies, Treg cells have been demonstrated to suppress immune responses in the periphery of leprosy patients and markers associated with Treg cells, mostly CD25, TGF-1, IL-35, CTLA4, IL-10, and FoxP3." (PMID 37153623, 2023). "By flow cytometry, we determined the intracellular production of IL-10 by enriched PD-1neg Tregs and PD-1+ Tregs in leprosy patients and healthy controls." (PMID 37153623, 2023). "We previously demonstrated that IL-10 producing Bregs influence T cell fate in a functionally distinct way in leprosy patients." (PMID 37153623, 2023). "We have previously demonstrated that interleukin 10 inhibits T-cell proliferation in leprosy patients through a mechanism in which the immune system is suppressed." (PMID 37153623, 2023). "All these data suggested an important role of IL-10 in regulation of immune response and the progression of leprosy." (PMID 36972292, 2023). "Our study confirmed that blocking of PD-1 increases suppressive activity of Tregs in leprosy patients in IL-10 dependent fashion." (PMID 37153623, 2023).
leprosy (continued). "The frequency of IL-10 producing Bregs also found high in leprosy patients, and it is involved in the pathogenesis of leprosy." (PMID 37153623, 2023). "We found PD-1 expressing Tregs secreting very less amount of IL-10 compared to PD-1neg Tregs which is secreting very amount of IL-10 in leprosy patients." (PMID 37153623, 2023). "With this intention, we investigated the effect of PD-1 expression on IL-10 production by Tregs in leprosy patients as IL-10 is one of the main immunosuppressive cytokines secreted by Tregs." (PMID 37153623, 2023). "IL-10 secreted by different immune cells plays important roles in the progression and phenotype of leprosy through regulation of both innate and adaptive immune responses." (PMID 36972292, 2023). "For example, polymorphisms in certain genes such as IL10, ninjurin 1 and TNF have been associated with leprosy susceptibility." (PMID 35492305, 2022). "Another study also indicated CD25hi Bregs that secrete IL-10 are a subgroup of cells with different functions that affect the fate of T cells in patients with leprosy." (PMID 35083339, 2022). "Cytokines level before the introduction of vaccination suggested that leprosy cured group have relatively high concentration of IL-6, IL-10, TNF, INF-γ and IL-17 compare to control group." (PMID 34397815, 2021). "In a BT-like murine model of leprosy, IL-10 suppression significantly augmented M-leprae-specific CD4+ and CD8+ T cell infiltration and permitted CD4+ T cells to penetrate and fragment nerve tissue." (PMID 34746168, 2021). "At day 0, leprosy cured group have relatively high concentration of interleukin-6, interleukin-10, tumor necrosis factor, interferon-γ, and interleukin-17 compared to control group." (PMID 34397815, 2021). "The frequencies of IL-10 (-819) TT and IL-10 (-1082) GG genotypes were significantly higher in leprosy patients as compared to healthy controls." (PMID 32849660, 2020). "Interleukin-10 (IL-10) is an immunosuppressive cytokine, found to be elevated in leprosy that accounted for the suppression of host’s immune system by regulating the functions of other immune cells." (PMID 32849660, 2020). "The expression of the IL-10, was also significantly higher in the TT genotypes of leprosy patients as compared to CC genotype." (PMID 32849660, 2020). "To answer this, we have evaluated the expression of IL-10 in T helper and Treg cells of leprosy patients." (PMID 32849660, 2020). "These sustained high levels of IL-10 are necessary to lead leprosy to a chronic and T cells unresponsive state." (PMID 32849660, 2020). "IL-10-producing regulatory B cells transformed T effector cells into Tregs, thus enhanced regulatory T cells functions in human leprosy." (PMID 32849660, 2020). "Increased IL-10 production has been observed in leprosy patients and up-regulation of IL-10 is a vital mechanism in the suppression of T cell-driven immune response." (PMID 32849660, 2020). "Lower levels of IL-10, an anti-inflammatory cytokine, were noted in the group of patients with leprosy neuropathy in combination with neural pain." (PMID 32038662, 2020). "Our present data demonstrates that IL-10 −819 TT genotype frequency was greater among the leprosy patients than the control subjects." (PMID 32849660, 2020). "A total of 132 lepromatous leprosy patients and 120 healthy controls were analyzed for IL-10 cytokine gene polymorphisms using PCR-SSP assay and flow cytometry was used to analyze IL-10 secretion by CD4 and Tregs in various genotype of leprosy patients." (PMID 32849660, 2020). "Expression of the IL-10 also measured in skin of leprosy patients bearing TT and CC genotypes at −819 position." (PMID 32849660, 2020). "This again highlights that IL-10 producing immune cells are possibly recruited at the lesioned sites (which is more in TT genotype) of leprosy patients, where they facilitate their characteristic suppressive action." (PMID 32849660, 2020).
leprosy (continued). "This supports previous studies which found that the autophagy inhibiting cytokine IL-10 is predominant in multibacillary leprosy compared to high levels of IL-26, IFN-γ, and TNF-α, autophagy inducing cytokines, found during paucibacillary tuberculoid leprosy." (PMID 33519771, 2020). "To evaluate the functional enrichment of Treg cells in various genotypes (CC, CT and TT) in leprosy patients, we measured intracellular IL-10 production by flow cytometry, using PBMCs derived from leprosy patients." (PMID 32849660, 2020). "Increased IL-10 levels in serum of TT bearing genotype at IL-10–819 position as compared to CC genotype in leprosy patients further complemented these results." (PMID 32849660, 2020). "The second reported subset is IL-10 producing Breg, and this subset was also demonstrated to show an increased frequency in PBMCs of leprosy patients as compared to healthy controls." (PMID 32373110, 2020). "IL-10, secreted by monocytes/macrophage, T cell subsets (Th2, Tregs) and B regulatory cells shows immune regulatory effects in case of human leprosy." (PMID 32849660, 2020). "We observed elevated levels of IL-10 in −819TT and −1082GG genotypes in the serum of leprosy patients as compared to other genotypes." (PMID 32849660, 2020). "Percentage of IL-10 producing Treg cells (CD4 + CD25 +) was significantly higher among TT genotypes in leprosy patients compared to that of CC and CT genotypes of leprosy patients (P = 0.0003)." (PMID 32849660, 2020). "Frequency of GG genotype at IL-10 −1082 position was also higher in the leprosy patients as compared to healthy control." (PMID 32849660, 2020). "IL-10 produced by various immune cells such as Tregs, Th2, Bregs and other cells suppresses the immune system of host and responsible for T cell anergy in leprosy patients." (PMID 32849660, 2020). "Sandwich ELISA was done in the culture supernatants of healthy and leprosy patients to detect IL-4, IL-10 and IFN-γ." (PMID 30642265, 2019). "Detection of Th1 cytokine IFN-γ and Th2 cytokines IL-4 and IL-10 in the PBMCs confirmed Th1/Th2 polarization of immune response in leprosy patients." (PMID 30642265, 2019). "For the cytokine analyses, the IL-10 expression was relatively higher in the leprosy reaction group (4.31 ± 0.83) when confronted with reaction-free leprosy patients (1.25 ± 0.53) (p = 0.003)." (PMID 31781675, 2019). "This encouraged us to block the IL-10 secreted cytokines Bregs in vitro in the PBMC culture of leprosy patients and see its impact on the effector T cells and Tregs in terms of activity." (PMID 30083152, 2018). "Collectively, these findings demonstrate that IL-10 producing Breg cells play an important mechanism in controlling the immunopathogenesis of leprosy and have an immunomodulatory effect on Tregs and effector T cells." (PMID 30083152, 2018). "These Breg cells also produce significant amounts of immunosuppressive IL-10 in leprosy patients BL/LL and BT/TT demonstrating that these cells are suppressive in nature." (PMID 30083152, 2018). "In this study, we aim to elucidate the effect of IL-10 producing Bregs derived from leprosy patients on effector T cells and Tregs activity." (PMID 30083152, 2018). "Several genes have been associated with leprosy, such as NOD2, PARK2/PARCG, LRRK2, RIPK2, TNF/LTA/HLA, LACC1, IL10, TLR1, and microRNA (miR)-146a." (PMID 29755459, 2018). "In contrast, infection of IL-10-derived MΦ, similar to MΦ in lesions from patients with the progressive form of leprosy, resulted in induction of type I IFN and suppression of the vitamin D directed pathway." (PMID 30300363, 2018). "Here, we evaluated the role of IL-10 producing Bregs in the pathogenesis of leprosy and assessed their immunoregulatory effects on Tregs and effector T cells." (PMID 30083152, 2018). "TNFA and IL10 genetic variants are classic risk factors for leprosy; gene products TNF-α and IL-10 are major signature cytokines for the tuberculoid and lepromatous pole, respectively." (PMID 30079069, 2018).